EGR2 (early growth response 2)
Diseases named in the same sentence as EGR2 in open-access papers (continued):
Sharing a sentence is not in itself a finding about the gene and the disease.
infection (27 papers, 2010 to 2025). The state of being infected such as from the introduction of a foreign agent such as serum, vaccine, antigenic substance or organism. "In the reciprocal experiment, the transfer of P14 cells from LCMV-Cl13 infection into LCMV-Arm infected hosts caused loss of EGR2 expression relative to cells transferred into control LCMV-Cl13 infected mice." (PMID 33986293, 2021). "In contrast, four (ULBP1, EGR3, RAET1K, EGR2) genes were downregulated in uninfected cells (GFP- pHrodo-) relative to the other three infection outcomes." (PMID 40630957, 2025). "In a resting state, a higher percentage of APN−/− AMs were CD38+ and lower percentage were Egr2+ when compared to WT, while upon infection with A. fumigatus, percentages of both CD38+Egr2− and CD38-Egr2+ cells increased." (PMID 38979340, 2024). "Transcriptional profiles of the genes CD38, Gpr18, Fpr2 (markers of classically activated macrophages), Arg1, and Egr2 (markers of alternatively activated macrophages) are significantly activated after infection with all viruses." (PMID 38473707, 2024). "CD4+ TNF expression was significantly lower in persistent infection compared to active infection (p=0.0058) as was CD4+ EGR2 (p=0.020)." (PMID 36439147, 2022). "Transfer of P14 cells from LCMV-Arm infection into LCMV-Cl13 infected hosts led to increased EGR2 expression relative to P14 cells transferred into control LCMV-Arm infected mice." (PMID 33986293, 2021). "During acute LCMV-Arm infection, EGR2 expression initially spiked above naive CD8+ T cell levels at day 5 post-infection (p.i.)before dropping below naive levels after viral clearance from day 8 p.i. onwards." (PMID 33986293, 2021). "In contrast, during chronic LCMV-Cl13 infection, EGR2 was significantly higher than in LCMV-Arm infection from day 8 p.i. onwards, and remained elevated in antigen-specific CD8+ T cells throughout infection." (PMID 33986293, 2021). "In contrast to chronic LCMV infection, and consistent with the limited expression of EGR2 during acute LCMV infection, EGR2 loss had little impact upon effector and memory CD8+ T cell differentiation during LCMV-Arm infection." (PMID 33986293, 2021). "In this model, we also found that some genes exhibited a downward trend (e.g., Ptgs2, Rel, IL4r, CXCL1, CXCL2, TLR5, Nfatc3 and Egr2) in M. fortis after infection." (PMID 28900150, 2017). "Lenti-miRZip-128a infection decreased the levels of mature miR-128a and significantly enhanced the expression of Lin28A, EGR2, ZFP36 and ANXA1." (PMID 28569789, 2017). "Previous studies demonstrated that genes encoding transcription factors such as c-jun, junB, EGR1, and EGR2 were amongst the host genes that were the most rapidly upregulated following infection." (PMID 21479245, 2011). "Further, after statistical validation, JUNB, ATF3 and EGR2 genes were attained, which may be used as potential biomarkers with Candida species infection." (PMID 35314002, 2022). "Moreover, EGR2 loss diminished the expression of multiple inhibitory receptors (PD-1, 2B4 and TIM3) within tetramer+ CD8+ T cells over the course of infection, while CD160 and LAG3 were either unchanged or even elevated within cKO cells." (PMID 33986293, 2021). "Egr2 and GRAIL are linked with the development of an anergic-like T cell phenotype in Type 2 (Fasciola hepatica) and Type 1 (Trypanosoma cruzi and Mycobacterium tuberculosis) infection settings." (PMID 31815932, 2019). "Eight days postinfection, an increase in T-bet– and IFN-γ–expressing CD4 T cells was detected in CD2-specific Egr2/3−/− mice, suggesting that the high levels of T-bet–expressing T cells in CD2-specific Egr2/3−/− mice result from hyperactivation of T cells at late stages of infection." (PMID 28455436, 2017). "Egr2 and 3 are highly induced in naive T cells at the early stages of responses to infection and antigen stimulation in vivo, suggesting that Egr2 and 3 may regulate T cell–mediated adaptive immune responses." (PMID 28487311, 2017).
infection (continued). "In response to infection, T-bet and Egr2 were induced in CD4 and CD8 T cells." (PMID 28455436, 2017). "Although we cannot explain the differences, Egr2-knockout models from different laboratories showed normal T cell responses to infection, suggesting that Egr2 single deficiency does not affect the function of T cells in adaptive immune responses." (PMID 28455436, 2017). "Reinduction of Egr2 and 3 after reencounter with antigen in vivo indicates that T cells can constantly adjust the extent of their proliferation and differentiation during the course of an infection, according to the levels of antigens and inflammation." (PMID 28487311, 2017). "The results demonstrated that Egr2 was reinduced during infection of recipient mice." (PMID 28487311, 2017). "Egr2 and 3 are induced in naive T cells by infection or antigen stimulation in vivo." (PMID 28487311, 2017). "In other infections EGR2 expression is often accompanied by EGR1 and c-FOS." (PMID 21490959, 2011). "In order to test the response to this parasite in EGR-2 deficient mice, 8 CKO and 8 WT mice were infected with Toxoplasma gondii intraperitoneally and serum IFN-γ levels were measured at days 7 and 22 after infection." (PMID 20886122, 2010). "Thus, FR4+Egr2+ MP cells can serve as functional Tfh cells in response to pathogen infection." (PMID 39568245, 2025). "Furthermore, upon 2-day AF infection, we detected a substantially higher colony formation capacity of Egr2fl/fl lung homogenates compared with Egr2+/+ ones, establishing the role of myeloid EGR2 in antifungal response in vivo." (PMID 39042472, 2024). "Using cell-specific ablation of Egr2 and mixed bone marrow chimeric mice, we show that cell-intrinsic EGR2 is indispensable for the tissue-specific identity of alveolar macrophages and their ability to control infection with a major respiratory pathogen, Streptococcus pneumoniae." (PMID 34797692, 2021). "Active infection could maintain EGR2 via antigen or inflammatory signals." (PMID 33986293, 2021). "Consistent with the results from CD2-Egr2/3−/− mice, Egr2/3-deficient retrogenic OT1 cells had severe defects in proliferation but were highly activated and produced excessive levels of effector cytokines compared with WT retrogenic-OT1 cells in response to OVA-VVWR infection." (PMID 28487311, 2017). "PTGER2 was significantly upregulated in both CD4+ (p=0.0039) and CD8+ (p=0.0086) T cells in active infection, as were CD4+ TNF expression (p=0.0364) and CD4+ EGR2 expression (p=0.0069)." (PMID 36439147, 2022). "Cd4-cre+Egr2f/f mice (cKO), or Cd4-cre+Egr2+/+ littermates (WT), were infected with LCMV-Cl13 and the response to infection was assessed." (PMID 33986293, 2021). "In contrast to our previous results, recent findings suggest that Egr2 is important for T-bet expression and IFN-γ production by effector T cells in response to infection." (PMID 28455436, 2017). "Additionally, we identified three critical targets during VVTT infection—ARC, JUNB, and EGR2—and further validated these targets using qPCR." (PMID 39940969, 2025). "Uninfected BMDM did not appreciably express CD38 or Egr2, markers of classically (M1) and alternatively (M2) activated macrophages, respectively, nor did infection change the lack of polarization." (PMID 28278296, 2017). "Additionally, retro-miR-150 infection of mir-150−/− CD8+ T cells reduced expression of anergy-related genes Cbl-b, Egr2, and p27 and increased the expression of activation-induced molecules granzyme B, cyclin B1, and Blimp1 following anti-CD3/CD28 stimulation." (PMID 28572627, 2017). "In a resting state, a higher percentage of APN-deficient AMs were CD38+ and lower percentage were Egr2+ when compared to WT, while after 10 hours of infection with A. fumigatus, percentages of both CD38+Egr2- and CD38+Egr2+ cells increased, with no change in CD38-Egr2+ cells." (PMID 40096083, 2025).
infection (continued). "Of those tested Cdc42ep3 (CDC42 effector protein), ARHGDIB (Rho GDP dissociation inhibitor (GDI) beta), Acta2 (Alpha actin 2), Egr2 (Early growth response 2), IL-6 (Interleukin 6) and Vav3 (vav 1 guanine nucleotide exchange factor), were induced by EPEC infection but not by infection with EPEC Δtir." (PMID 21490959, 2011).
peripheral neuropathies (10 papers, 2007 to 2026). "The location of the mutation in EGR2, and the effect in protein function determine the type of peripheral neuropathies, as well as the severity of the disorder." (PMID 41595476, 2026). "Specifically, EGR2 was upregulated, which encodes for a transcription factor that is essential for myelination of the nervous system, and defects result in peripheral neuropathies." (PMID 34055930, 2021). "Individuals with mutations in EGR2 develop peripheral neuropathies due to the crucial role for EGR2 in Schwann cell function." (PMID 34797692, 2021). "The severity and onset of peripheral neuropathy caused by EGR2 variants is highly heterogenous, and it is yet to be determined why this broad phenotypic variability exists." (PMID 31852952, 2019). "This study adds further support to the heterogeneity of EGR2-related peripheral neuropathies and provides strong functional evidence for the pathogenicity of the p.Asp411Gly EGR2 variant." (PMID 31852952, 2019). "The spectrum of peripheral neuropathy associated with disease-causing EGR2 variants ranges from severe early onset DSN and CHN, to later onset demyelinating CMT1 and axonal CMT2." (PMID 31852952, 2019). "Pathogenic variants in the EGR2 gene (early growth response 2) cause a broad spectrum of peripheral neuropathy phenotypes." (PMID 31852952, 2019). "Because of the myelination defect in peripheral nerves of Egr2 knockout mice, several groups have screened human patients with peripheral neuropathies for mutations in the EGR2 gene." (PMID 18096076, 2007). "The speculation that EGR2 acts as a transcription factor in response to various stimuli, including growth factors, stress, and mitogens, means that this protein affects myelin genes and hence, peripheral neuropathies may result from mutations in it." (PMID 41595476, 2026). "However, in peripheral neuropathy disease context, elevated axonal NRG1t3 improves remyelination and myelin sheath thickness without increasing Egr2 expression or activity, and without affecting the transcriptional activity of canonical myelination genes." (PMID 38311982, 2024).
psychiatric disorder (3 papers, 2014 to 2022). A disorder characterized by behavioral and/or psychological abnormalities, often accompanied by physical symptoms. "The expression of EGR2 was associated with stress response and psychiatric disorders." (PMID 36432096, 2022).
brain diseases (1 paper, 2026). "The early growth response 2 (EGR2) gene has been studied in a variety of brain diseases." (PMID 42016821, 2026).
immune diseases (1 paper, 2022). "EGR2 is a member of a zinc finger transcription factor family, and it is widely involved in the occurrence and development of immune diseases and tumors." (PMID 37529797, 2022).
kidney diseases (1 paper, 2024). "Early growth response factor-1 and -2 (EGR1, EGR2) have been implicated as important pro-fibrotic transcription factors in kidney diseases." (PMID 37752256, 2024).
metabolic disorders (1 paper, 2021). "Two subsets with distinct differentiation states, involving 40 hub CDRGs regulated by YY1 and EGR2, were identified by single-cell RNA sequencing data, of which subset I was related to hypoxia, metabolic disorders, and inflammation, and subset II was associated with immune responses and ferroptosis." (PMID 34966734, 2021).
EGR2 also shares sentences with these, for which no sentence is quoted: leukemia (4 papers); congenital hypomyelinating neuropathy (3); epilepsy (3); lung carcinoma (3); acute myeloid leukemia (2); Alzheimer disease (2); aortic valve disease (2); atherosclerosis (2); colon cancer (2); Dejerine-Sottas syndrome (2); Huntington disease (2); ischemia (2); Neurological Disease (2); ovarian carcinoma (2); peripheral nerve injury (2); psychosis (2); sarcoma (2); schwannoma (2); type 2 diabetes (2); abdominal aortic aneurysm (1); acute myocardial infarction (1); adenoma (1); autism spectrum disorder (1); Behcet disease (1); celiac disease (1); Charcot-Marie-Tooth disease type 1D (1); Charcot-Marie-Tooth type 1 (1); cranial neuropathy (1); Crohn disease (1); cutaneous T-cell lymphoma (1).
A further 41 diseases each share a sentence with EGR2 in 1 paper.